MIR662 (microRNA 662)
Synonyms: hsa-mir-662; MIRN662
Gene: MicroRNA gene on chromosome 16 (770,183 to 770,277, forward strand). Ensembl gene ENSG00000207579.
Gene Ontology:
Biological process: miRNA-mediated post-transcriptional gene silencing